NOTCH3 (notch receptor 3)
Diseases named in the same sentence as NOTCH3 in open-access papers (continued):
Sharing a sentence is not in itself a finding about the gene and the disease.
tumor (continued). "In summary, these data show that gliotoxin recovers a non-canonical tumor-suppressing NOTCH3 activity, indicating that nuclear NOTCH2 inhibitors might be beneficial compared to pan-NOTCH inhibitors in the treatment of CLL." (PMID 32570839, 2020). "In line with this concept, Notch3 has been recognized as a pivotal driver required for survival and maintenance of NSCLC CSCs both in humans and mice, and recent findings indicate that Notch3 silencing inhibits EMT, decreases tumor cell proliferation, and induces apoptosis in NSCLC cells." (PMID 32784481, 2020). "Among the 59 urothelial cancer samples examined, two showed lower Notch3 expression than the matched non-tumor tissue (non-tumor tissue from the same patient); four samples showed Notch3 expression level equal to that in matched non-tumor tissues, and 53 samples showed higher levels of Notch3." (PMID 28416766, 2017). "We next looked at the vascularization of tumours grown in the absence of stromal Notch3 expression." (PMID 28719575, 2017). "In light of our previous report that Notch3 overexpression correlated with distant metastasis in HGSC, and that angiogenesis and migration are well known important factors governing tumor progression and metastasis, it is suggested that Notch signaling pathway may be involved in these processes." (PMID 29069826, 2017). "However, we report here that the tumour growth inhibitory effect of DAPT treatment was no longer observed in Notch3 mutant mice." (PMID 28719575, 2017). "Interestingly, the only Lck-Dlx5 tumor (1/11) without overexpression of Notch1 and Notch3 instead showed upregulation of Notch2, further suggesting an essential role for aberrant Notch signaling in Dlx5-driven T-cell lymphomagenesis." (PMID 28122332, 2017). "Interestingly, although Notch3 has been shown to be involved in different pathological settings affecting the vasculature, its role in tumour vasculature has never been addressed." (PMID 28719575, 2017). "NOTCH3(+)CAFs may promote sprouting of tumor endothelial cells by a molecular mechanism similar to that of the DLL4/NOTCH1 pathway and stabilize the newly formed tumor vessels through JAG1/NOTCH3 interactions between endothelial cells and CAFs." (PMID 27124156, 2016). "Paralog-specific effects may be prominent in these tumors, and there is some preliminary evidence that Notch1 and perhaps Notch3 act as a tumor suppressors in some of NETs but not in others." (PMID 27148486, 2016). "The tumor inhibition rate was evaluated, followed by the quantification of messenger ribonucleic acid (mRNA) and protein expression of notch signaling components NOTCH-1, NOTCH-3, NOTCH-4, JAG-1, DLL-4, Hes-1, and Hey-1 using quantitative polymerase chain reaction (qPCR)." (PMID 26762567, 2016). "However, Notch3 and AFP co-existed in only a subset of the tumor cell population." (PMID 25668819, 2015). "To determine whether WWP2 expression affects tumor development, we ectopically expressed WWP2 in SKOV3-CR cells which were pre-established to develop carboplatin resistance (CR) phenotype and expressed abundant Notch3." (PMID 25356737, 2014). "They found low levels of Notch3 staining in normal prostate sections and decreased Notch2 expression with increasing tumor grade but did not report whether they detected Notch2 in normal prostate tissue." (PMID 24199173, 2013). "The putative Notch-independent role for Jagged1 in human neoplasms is not clear, and our results did not demonstrate that Jagged1 upregulation affected the expression level of Notch3, suggesting that the autoregulatory loop was “one way”—from Notch3 to Jagged1." (PMID 20953350, 2010). "Interestingly, NOTCH3 expression had a negative association with well-documented predictive biomarkers of immune checkpoint blockade (ICB) immunotherapy, including tumor mutation burden (TMB), gene expression profiling (GEP) score and innate anti-PD-1 resistance (IPRES) signature." (PMID 33479597, 2020).
tumor (continued). "The in vivo tumor formation assay suggested that hsa_circ_0058124 knockdown dramatically inhibited tumor growth when compared to the negative control group, whereas suppression of NOTCH3 or GATAD2A partly abolished this reduction of tumor growth by hsa_circ_0058124 knockdown." (PMID 31324198, 2019). "However, Notch3 implication in tumour vasculature has not been addressed." (PMID 28719575, 2017). "Having previously reported that Notch3 activation appeared to be associated with more aggressive disease, we have now examined components of this pathway (Notch1, Notch3, Notch4, HES-1, HEY-1) in more detail in resectable (n = 42) and non-resectable (n = 50) tumours compared to uninvolved pancreas." (PMID 23226563, 2012). "Later, Maraver and colleagues confirmed the tumour suppressive role of NOTCH1, but they observed another role for NOTCH2, whereas NOTCH3 was not studied." (PMID 41008920, 2025). "Here, the expression of COL5A3, FN1, and NOTCH3 was more specific to α-SMA-positive stromal cells rather than tumor cells, while IGFBP3 was overexpressed in both tumor and stroma in comparison to adjacent non-tumor tissues." (PMID 40522948, 2025). "LEC priming induced an increase in Notch3 expression specifically in the metastatic cell lines, namely WM852 and WM165, but not in the primary tumor derived WM793 or Bowes." (PMID 29712618, 2018). "In the tumor microenvironment of BC, a secreted protein named Cartilage Oligomeric Matrix Protein (COMP) physically bridges Notch3 and JAG1 on the cell membrane of CSCs, thus driving JAG1/Notch3 signaling and subsequently activating the β-catenin and Akt signaling pathways to maintain CSC status." (PMID 34195229, 2021). "However, we did not analyze in detail the prognostic markers influencing tumor sensitivity to Gemcitabine, such as, e.g., ENT1, Notch3 or MiR-21." (PMID 33114652, 2020). "Noticeably, this latter work also disclosed that unlike Notch1 or Notch3, which displayed increased levels, Notch2 was decreased in advanced tumors in the KrasG12D NSCLC model, where it furthermore displayed a tumor suppressor function through modulation of the Wnt/β-catenin pathway." (PMID 32784481, 2020).
cancer (260 papers, 2009 to 2026). A tumor composed of atypical neoplastic, often pleomorphic cells that invade other tissues. "Additional clustering and dimensionality reduction, utilizing four marker genes (ACTA2, FAP, PDGFRB, and NOTCH3), resulted in the delineation of four cancer-associated fibroblast (CAF) subpopulations." (PMID 40589759, 2025). "Among the gene mutations that significantly co-occurred with copy number amplifications (CNAs), two genes showed association in multiple cancer types: NOTCH3 in BRCA and LUAD, and EGFR in LGG and LUAD." (PMID 41415395, 2025). "Overall, these results suggest that FGA and NOTCH3 expression levels are strongly linked to various survival outcoomes across different cancers." (PMID 39130639, 2024). "Overexpression and aberrant activation of the Notch3 gene are linked to cancer, particularly breast and ovarian cancer." (PMID 38790158, 2024). "The expression of NOTCH3 by cancer-associated fibroblasts has a paracrine effect in cancer cells; for this reason, it was suggested as a marker of poor prognosis in OSCC patients." (PMID 37445908, 2023). "COMP has been reported to be implicated in the EMT and other well-known cancer cell signaling pathways, such intracellular calcium homeostasis, Notch3, Akt, MEK/ERK, etc.." (PMID 36671447, 2022). "We conducted a similar analysis using NOTCH3, which also was associated with improved survival in the pan-cancer cohort." (PMID 35798829, 2022). "Similar Notch3 modulation was shown for the first time in co-cultures with HGSOC patients’ ascites-derived cancer-associated fibroblasts and Jagged1-expressing EOC cell lines." (PMID 35884426, 2022). "By contrast, this review mainly focuses on the underlying Notch3-related molecular mechanisms that regulate cancer stemness and chemoresistance." (PMID 34195229, 2021). "Among the four receptors (Notch1-4) in the Notch family, accumulated evidence has shown the overexpression of Notch3 to be associated with recurrence and metastasis in some cancer types)." (PMID 35118116, 2021). "According to TCGA, the Notch3 gene was altered in 5% of cancer samples, mainly via amplification and mutation." (PMID 34195229, 2021). "Caused by its overexpression in several types of cancers, NOTCH3 has already been investigated as a target for anticancer drugs." (PMID 33029756, 2020). "Research has shown that Notch 3 is associated with a higher invasiveness and metastatic rate in many cancer types." (PMID 33374160, 2020). "This included E74 like ETS transcription factor 3 (ELF3), spen family transcriptional repressor (SPEN) and notch receptor 3 (NOTCH3) that are known to be mutated in various cancers." (PMID 31438645, 2019). "T-ALL is a malignancy characterized by aberrant Notch signaling, sustained by activating mutations in Notch1 as well as overexpression of Notch3, a Notch paralog physiologically subjected to lysosome-dependent degradation in human cancer cells." (PMID 29643474, 2018). "It has been demonstrated that aberrant activation of NOTCH3 signaling is associated with the pathogenesis of NSCLC by favoring cancer cells survival, proliferation, invasion, migration, and stemness." (PMID 29765324, 2018). "In this study, we investigated the roles of NOTCH3 signaling in cancer associated fibroblasts (CAFs) in OSCCs." (PMID 27124156, 2016). "While mycobacterial infection was previously shown to induce TLR2-NOTCH1-PI3K-mTOR-NF-κB pathway to regulate immune responses, different cancer studies have implicated NOTCH3-dependent MSI1 expression and MSI1-dependent NOTCH activation." (PMID 27532872, 2016). "It has been shown that dysregulation of Notch3 is associated with tumorigenesis in various cancers." (PMID 41027955, 2025). "Overexpression of Notch3 is also associated with cancer development." (PMID 37550405, 2023). "Interestingly, NOTCH3 oncogenic signaling has been implicated in invasiveness and metastasis of various cancer types." (PMID 37318881, 2023).
cancer (continued). "This negative correlation may result from the increased expression of LSD1 in cancer-associated fibroblasts (CAFs), which regulate driving NOTCH3-mediated self-renewal of cancer stem cells." (PMID 36059955, 2022). "Diverse types of cancers such as gastric, cervical, colorectal, hepatocellular, lung, ovarian, pancreatic, and prostate are accompanied by elevated expression of Notch-3 and have been associated with rapid malignant progression, poorer prognosis, abnormal differentiation, and metastasis." (PMID 36017236, 2022). "Notch3 has been widely reported to be associated with cancer development." (PMID 35118116, 2021). "Notch3 overexpression in cancer is mainly caused by alterations of the Notch3 gene." (PMID 34195229, 2021). "Importantly, MDA-MB-231 LM and matching parental cells expressed nominal levels of NOTCH1 and NOTCH2, suggesting that LY411575-mediated inhibition of cancer cell seeding and metastatic growth was primarily linked to inhibition of the NOTCH3 signaling pathway." (PMID 30180881, 2018). "Importantly, because MDA-MB-231 LM and parental cells showed nominal levels of NOTCH1 and NOTCH2, these results suggest that LY411575-mediated inhibition of cancer cell seeding and metastatic growth was likely associated with NOTCH3 targeting." (PMID 30180881, 2018). "Since NAC as a ROS scavenger is presumably cancer preventive, at least when functioning at the site of production, future studies are warranted to understand whether Notch3-expressing cancer cells display increased susceptibility to NAC treatment in vivo." (PMID 27102435, 2016). "Therefore, miR-150 targeting Notch3 might be associated with chemoresistance as well as cancer development." (PMID 29069826, 2017). "Abnormal activation of Notch signaling is involved in the etiology of various diseases, including cancer, but the association between Notch3 expression in urothelial cancer and clinical outcome remains unclear, and the molecular mechanisms underlying Notch3 signaling activation are not well defined." (PMID 28416766, 2017). "scRNA-seq analysis revealed enhanced PVR-TIGIT interactions between cancer and immune cells in NOTCH3-high tumors." (PMID 41808828, 2026). "For example, NAT10 increases the notch receptor 3 (NOTCH3) mRNA level by improving mRNA stability via acetylation in cancers." (PMID 40226364, 2025). "Notch3’s mRNA high expression was demonstrated to have prognostic value for better OS for cancer patients." (PMID 40804837, 2025). "Non-coding RNAs, antibodies, and antibody–drug conjugates, as treatment strategies to block Notch3 signaling, can provide precise targeted cancer therapy." (PMID 40804837, 2025). "Analysis of copy number variation (CNV) in FGA and NOTCH3 across 20 different cancer types revealed distinct CNV rates." (PMID 39130639, 2024). "The association between high NOTCH3 expression and poor COAD prognosis is a significant finding, consistent with previous studies implicating Notch signaling in cancer progression." (PMID 39130639, 2024). "Further investigations revealed that IL-8 promotes cancer cell stemness induction via Notch3, with a positive correlation observed between elevated IL-8 levels in ascites and Notch3 expression in OC tissues." (PMID 38903506, 2024). "In this study, we conducted a comprehensive assessment of the relationship between NOTCH3 and the prognosis of cancer patient using databases including Oncomine, PrognoScan and Kaplan–Meier plotter." (PMID 38906903, 2024). "Our results indicate an association between NOTCH3 expression and poor prognosis in COAD, suggesting its involvement in cancer cell survival and proliferation through interaction with the PI3K-Akt pathway." (PMID 39130639, 2024). "Fibronectin Leucine-Rich Transmembrane Protein 2 (Fibroleukin, FGA) and NOTCH3, known for their roles in muscle adptation and cancer progression, are particularly intriguing in this context." (PMID 39130639, 2024).
cancer (continued). "Mechanistically, the membrane-bound COMP induced EMT and cancer stemness via the activation of the Notch3 axis." (PMID 38615020, 2024). "In essence, the activation of Notch3-mediated signal transduction through IL-8 secretion from CAFs and cancer cells significantly contributes to promoting stemness in human OC." (PMID 38903506, 2024). "Further differential expression analysis of FGA and NOTCH3 across these cancers highlighted significant gene expression differences, with overall changes shown in a bar plot and specific changes depicted in a dot plot." (PMID 39130639, 2024). "NOTCH3, a member of the Notch receptor family, plays a multifaceted role in tumorigenesis, influencing various aspects of cancer biology including cell proliferation, differentiation, angiogenesis, and apoptosis." (PMID 39286249, 2024). "NOTCH3 also plays a role in supporting cancer stemness and resistance to therapy, which can be circumvented by the use of NOTCH inhibitors since they reduce the expression of stem cell markers and improve response to chemotherapy and radiotherapy." (PMID 39061234, 2024). "Recent studies have highlighted the significance of the Notch signaling pathway, which includes NOTCH3, in muscle adaptation and its frequent dysregulation in cancers, including COAD." (PMID 39130639, 2024). "An important pan-cancer single cell RNA sequencing analysis comprising of the stromal cells from 10 different solid tumors identified significant enrichment of NOTCH3 and HES4 in CAFs compared to normal fibroblasts." (PMID 38269089, 2023). "The underlying molecular mechanism involves the activation of Notch3 by its ligand Jagged1 bridged together by COMP, which leads to a generation of a higher proportion of cancer stem cells." (PMID 37207219, 2023). "Recent studies have also demonstrated the therapeutic efficacy of Notch-3-inhibiting antibodies and Notch-3-targeted antibody–drug conjugate in multiple murine cancer models." (PMID 37308977, 2023). "Other cancer-related gene mutations identified by our WES analysis included SATB2, NOTCH3, STAG2 and TET2." (PMID 38201285, 2023). "The mixed expression and contribution of Notch3 in stromal or cancer cells points to the importance to study survival impact with protein staining rather than RNA-seq bulk sequencing." (PMID 36854682, 2023). "In OSCC, the expression of neurogenic locus notch homolog protein 3 (NOTCH3) plays an essentially role in angiogenesis regulation, promoting cell–cell contact between fibroblasts and cancer cells." (PMID 37445908, 2023). "Since miR-206 is multifunctional, mechanisms by which LINC00707 affects cancer cell functions involves various miR-206-target mRNAs; NOTCH3 controls cell proliferation, and formin-like 2 regulates cell migration." (PMID 37784093, 2023). "Zfhx3 and Notch3 in the HIF-related cancer signal pathway were upregulated under hypoxia, while phosphatase, tensin (Pten), and receptor tyrosine-protein kinase (Errb2) were downregulated after continuous hypoxia." (PMID 36147561, 2022). "Cartilage Oligomeric Matrix Protein (COMP) controls the cancer stem cell population via increasing Notch3 and Jag-ged1 interaction which results in increased Notch3 signaling activation." (PMID 36017236, 2022). "WT mouse CRIPSCs also had higher expression of the genes related to stem cells (Psca, Atg9b, Sox2, Sox9), cell cycle (Cdk6), mammary luminal progenitor cells (Notch3 and Notch1), and cancers." (PMID 35841025, 2022). "Our findings provide new insights into a potential strategy for cancer therapy by targeting both Notch3 and ferroptosis." (PMID 35258176, 2022). "Taken together, our findings provide new insights into a potential strategy for cancer therapy based on targeting Notch3 and ferroptosis." (PMID 35258176, 2022).